NCAPG2 (non-SMC condensin II complex subunit G2)
Description:
Regulatory subunit of the condensin-2 complex, a complex which establishes mitotic chromosome architecture and is involved in physical rigidity of the chromatid axis.
Synonyms: CAP-G2; hCAP-G2; LUZP5; FLJ20311; MTB; 3KS; CAPG2
Tractability: PROTAC: ubiquitination databases record sites on it.
Gene: Protein-coding gene on chromosome 7 (158,628,224 to 158,704,825, reverse strand). Ensembl gene ENSG00000146918.
Subcellular location: Nucleus
Subcellular location (Human Protein Atlas): Nucleoplasm; Nuclear speckles
Pathways (Reactome):
Cell Cycle: Condensation of Prophase Chromosomes
Gene Ontology:
Molecular function: histone H4K20me1 reader activity; protein binding; bHLH transcription factor binding
Biological process: mitotic sister chromatid segregation; cerebral cortex development; chromatin organization; mitotic chromosome condensation; positive regulation of chromosome segregation; positive regulation of chromosome separation
Cellular component: membrane; nuclear speck; nucleoplasm; condensin complex; nucleus; condensed nuclear chromosome; nuclear lumen
Genetic constraint (gnomAD): Loss-of-function variants: 39 observed, 115.48 expected, observed/expected ratio (o/e) 0.34, 90% interval 0.26 to 0.44. The upper end of that interval is the gene's LOEUF score, 0.44, which puts it in group 1 of 6, group 1 being the genes least tolerant of losing a copy. Missense variants: 950 observed, 1,276.8 expected, observed/expected ratio (o/e) 0.74, 90% interval 0.7 to 0.79. Synonymous variants: 458 observed, 459.72 expected, observed/expected ratio (o/e) 1, 90% interval 0.92 to 1.08.
Gene-disease validity (ClinGen):
ClinGen rates the evidence that NCAPG2 causes each of these diseases.
Khan-Khan-Katsanis syndrome (autosomal recessive): Limited.
Homologues: Orthologues: chimpanzee NCAPG2 (99% identical), macaque NCAPG2 (98% identical), dog NCAPG2 (87% identical), rabbit NCAPG2 (86% identical), guinea pig NCAPG2 (84% identical), pig NCAPG2 (82% identical), rat Ncapg2 (82% identical), mouse Ncapg2 (81% identical), tropical clawed frog ncapg2 (61% identical), zebrafish ncapg2 (46% identical), Caenorhabditis elegans capg-2 (17% identical).
Diseases named in the same sentence as NCAPG2 in open-access papers:
NCAPG2 is named in the same sentence as 51 diseases in open-access papers, as found by Europe PMC text mining. Sharing a sentence is not in itself a finding about the gene and the disease. The quoted sentences say what the papers report.
lung adenocarcinoma (12 papers, 2017 to 2025). A carcinoma that arises from the lung and is characterized by the presence of malignant glandular epithelial cells. "NCAPG2 contributes to tumor proliferation and is associated with poor prognosis among lung adenocarcinomas." (PMID 37248471, 2023). "High expression of NCAPG2 has been shown to be associated with poor prognosis in patients with lung adenocarcinoma and hepatocellular carcinoma." (PMID 37192046, 2023). "High levels of NCAPG2 expression were associated with shorter overall survival time in patients with lung adenocarcinoma, as evidenced by Kaplan Meier-plotter." (PMID 36059662, 2022). "High NCAPG2 expression is associated with advanced clinical tumor stage and reduced survival time in patients with lung adenocarcinoma, and PTTG1 has been correlated with non-small cell lung cancer progression and is an independent poor prognostic factor in patients with non-small cell lung cancer." (PMID 40559622, 2025). "In this study, the overexpression of miR186-5p was found to downregulate NCAPG2 expression and inhibit the progression of epithelial–mesenchymal transition in lung adenocarcinoma cells." (PMID 40559622, 2025). "Previous reports have suggested that NCAPG2 expression is strongly correlated with immune infiltration levels in lung adenocarcinoma progression." (PMID 35898895, 2022). "NCAPG2 was identified as an erlotinib resistance gene and maintained the stemness of lung adenocarcinoma." (PMID 36139554, 2022). "LncRNA-AC009948.5 promotes lung adenocarcinoma cells metastasis via the miR-186-5p/NCAPG2 axis and activation of the EMT process." (PMID 36059662, 2022). "Based on the results of the mRNA microarray, the expression of NCAPG2 in lung adenocarcinoma with lymphatic metastasis was 3.120532 times higher than that in a normal one." (PMID 36059662, 2022). "NCAPG2 level were found to be increased in non-small cell lung cancer, and its over-expression was found to be correlated with lymph node metastasis, thus enabling the use of NCAPG2 as a poor prognostic biomarker in lung adenocarcinoma." (PMID 31277598, 2019). "In addition, NCAPG2 was found to maintain the stemness and promote erlotinib resistance in lung adenocarcinoma." (PMID 36139554, 2022). "In summary, NCAPG2 is a promising prognostic factor, and its future application may help determine the optimal treatment strategy for lung adenocarcinoma." (PMID 35664767, 2022). "Rescue experiments were conducted to assess whether LncRNA-AC009948.5 promotes lung adenocarcinoma migration and invasion through the miR-186-5p/NCAPG2 axis." (PMID 36059662, 2022). "Clinicopathological data analysis showed that NCAPG2 overexpression was significantly correlated with lymph node metastasis and pathologic‐Tumour Nodes Metastasen stages, and was an independent prognostic factor in lung adenocarcinoma patients." (PMID 27862966, 2017). "Taken together, we demonstrated that increased NCAPG2 expression could regulate cell proliferation and identified as a poor prognostic biomarker in lung adenocarcinoma." (PMID 27862966, 2017). "Moreover, siRNA‐mediated knockdown of NCAPG2 could inhibit tumour cell growth of lung adenocarcinoma cells (A549 and H1299) in vitro and could significantly lead to cell cycle arrest in the G2 phase." (PMID 27862966, 2017).
hepatocellular carcinoma (7 papers, 2020 to 2025). A malignant tumor that arises from hepatocytes. "Meanwhile, NCAPG2 overexpression has also been found in hepatocellular carcinoma, and its higher expression was associated with adverse clinical outcomes." (PMID 35664767, 2022). "In hepatocellular carcinoma, the knockdown of NCAPG2 arrests tumor cells in the G1/S phase and reduces their migration and invasion abilities." (PMID 39917394, 2025). "It has been previously reported that miR-188-3p hepatocellular carcinoma proliferation and metastasis directly target NCAPG2." (PMID 33344773, 2020). "NCAPG2 was recently reported to directly bind with STAT3 to promote hepatocellular carcinoma." (PMID 38166947, 2024). "NCAPG2 overexpression drives Hepatocellular carcinoma (HCC) proliferation and metastasis by activating the STAT3 and NF-κB/miR-188-3p pathways." (PMID 36139554, 2022). "NCAPG2 was previously shown to directly interact with STAT3 and activate STAT3 signaling, thus driving hepatocellular carcinoma proliferation and metastasis." (PMID 38166947, 2024).
lung carcinoma (6 papers, 2017 to 2023). "To validate the prognosis of NCAPG2 in lung cancer, we subsequently determined the relationship between NCAPG2 expression and OS across different subgroups by various clinical features." (PMID 35664767, 2022). "UALCAN database results and immunohistochemistry (IHC) staining also suggested that the protein of NCAPG2 was upregulated in lung cancer tissues." (PMID 35664767, 2022). "Results confirmed that NCAPG2 was significantly increased in lung cancer tissues and cell lines, especially in A549 and H1650 cells." (PMID 35664767, 2022). "To validate the prognosis of NCAPG2 in lung cancer, we analyzed the GEO dataset and found that upregulation of NCAPG2 was correlated with poor prognosis in patients with lung cancer." (PMID 35664767, 2022). "We performed a correlation analysis between NCAPG2 and 13 lung cancer stemness markers using the TCGA database and found that NCAPG2 was highly correlated with ABCC1, MYC, and EPCAM." (PMID 36139554, 2022). "Results confirmed that NCAPG2 was significantly increased in lung cancer tissues compared to normal lung tissues." (PMID 35664767, 2022). "Here, for the first time we reported that NCAPG2 was evidently increased in non‐small cell lung cancer tissues compared to adjacent normal lung tissues." (PMID 27862966, 2017). "Our IHC assay also demonstrated that NCAPG2 was overexpressed in lung cancer." (PMID 35664767, 2022). "The upregulation of NCAPG2 promotes the proliferation of lung cancer cells." (PMID 36138066, 2022). "To validate that, we used GEO datasets to assess the NCAPG2 expression in lung cancer." (PMID 35664767, 2022). "Four other genes involved in the ceRNA network, including MCM7, NCAPG2, SETD6, and KIF22 have also been reported to involved in lung cancer progression." (PMID 37098483, 2023). "Taken together, NCAPG2 was upregulated in LUAD and might act as a pivotal player in the carcinogenesis of lung cancer." (PMID 35664767, 2022).
non-small cell lung carcinoma (5 papers, 2019 to 2025). A group of at least three distinct histological types of lung cancer, including non-small cell squamous cell carcinoma, adenocarcinoma, and large cell carcinoma. "According to previous non-small-cell lung cancer research, NCAPG2 is strongly correlated between NCAPG2 and immune infiltration levels." (PMID 37501987, 2023). "NCAPG2 has been shown to promote proliferation, migration, invasion, and epithelial–mesenchymal transition (EMT) in various cancers, such as liver cancer and non-small cell lung cancer." (PMID 37248471, 2023).
liver cancer (4 papers, 2021 to 2024). An epithelial or non-epithelial malignant neoplasm that arises from the liver. "Similar to our results, NCAPG2 is highly expressed in a variety of cancers, such as liver cancer and NSCLC." (PMID 34712733, 2021). "NCAPG2 transcriptional activity promotes liver cancer cell proliferation and migration." (PMID 38637125, 2024). "Studies of miR-375 among liver cancers have demonstrated that this resistance may function through modulation of Non-SMC Condensin II Complex Subunit G2 (NCAPG2), Interleukin 6 (IL-6) and Transforming growth factor-beta (TGF-β)." (PMID 36674758, 2023).
lymph node metastasis (4 papers, 2017 to 2024). "NCAPG2 upregulation is associated with advanced pathological grade, lymph node metastasis, and poor prognosis in certain cancers." (PMID 38166947, 2024). "Univariate regression analysis showed that EIF2S3, NCAPG2, the pathological stage, and lymph node metastasis were associated with the prognosis of LUAD patients." (PMID 36139554, 2022). "We found that high expression of NCAPG2 protein was correlated with lymph node metastasis and p‐TNM stages and contributed to adverse clinical outcome in lung AD patients." (PMID 27862966, 2017). "The difference by statistical analyses indicated that a high expression of NCAPG2 protein was also found to be significantly correlated with lymph node metastasis (P = 0.038) and pathologic‐Tumour Nodes Metastasen stage (p‐TNM stage) (P = 0.024)." (PMID 27862966, 2017). "Therefore, we used the clinical data and expression profile of TCGA-LUAD to analyze the association between the expression of NCAPG2 and EIF2S3, the clinical stage, and lymph node metastasis." (PMID 36139554, 2022).
glioblastoma (3 papers, 2022 to 2024). The most malignant astrocytic tumor (WHO grade IV). "NCAPG2 facilitates glioblastoma cell malignancy and xenograft tumor growth via HBO1 activation by phosphorylation." (PMID 36139554, 2022). "With respect to glioblastoma, NCAPG2 actively promotes cancer cell progression." (PMID 38637125, 2024).
glioma (3 papers, 2022 to 2023). A benign or malignant brain and spinal cord tumor that arises from glial cells (astrocytes, oligodendrocytes, ependymal cells). "Moreove, we utilized the Rembrandt and Gravendeel dataset to validate the expression of NCAPG2 in glioma." (PMID 35898895, 2022). "The results of the Cox regression analysis revealed that NCAPG2 was an independent factor for the prognosis of low-grade glioma." (PMID 35898895, 2022). "on glioma, which reinforced the prospective role of NCAPG2 in the field of immunotherapy." (PMID 36776838, 2023). "Finally, the protein level of NCAPG2 was highest in glioma than normal brain tissues based on our IHC assay results, consistent with the results from transcriptional analyses." (PMID 35898895, 2022). "Depletion of NCAPG2 significantly inhibited self-renewal of glioma stem cell (GSC) in vitro." (PMID 35898895, 2022). "Importantly, we found that NCAPG2 was highly expressed in glioma stem cells lines and knockdown of NCAPG2 significantly inhibited the self-renewal ability of GSC." (PMID 35898895, 2022). "Given that GSEA enrichment analysis above showed that NCAPG2 may be correlated with WNT signaling pathway, we therefore examined whether NCAPG2 affect self-renewal of glioma stem cell (GSC) in vitro." (PMID 35898895, 2022). "By reviewing previous studies, we found that CASP2, NCAPG2, BAZ1B, and ZNF800, the genes most positively related to NUP205, were reported as carcinogenic genes in cancer, especially CASP2, NCAPG2, and BAZ1B, which were found to be carcinogenic genes in glioma." (PMID 37284202, 2023). "In our study, the NCAPG2 and BAZ1B genes were positively related to NUP205 and have been reported as oncogenes for glioma." (PMID 37284202, 2023). "It has been established that NCAPG2 overexpression could potentially alter the signaling pathways, like STAT3 and NF-κB, or other oncogenes to promote proliferation and invasion of the malignancy cells in various cancers including liver cancer, melanoma, lung cancer and glioma." (PMID 36776838, 2023).
pancreatic cancer (3 papers, 2022 to 2024). "NCAPG2 appears promising as a potential biomarker to assess immune response and predict prognosis in pancreatic cancer patients." (PMID 38637125, 2024). "Our research demonstrated that hsa-miR-181a-5p might be a negative regulator of pancreatic cancer via target NCAPG2." (PMID 35664767, 2022).
breast carcinoma (2 papers, 2014 to 2024). "NCAPG2 emerges as a novel promoter in the setting of metastatic breast cancer, suggesting that it plays an important role in driving breast cancer incipience and progression." (PMID 38637125, 2024).
colorectal cancer (2 papers, 2024 to 2025). A primary or metastatic malignant neoplasm that affects the colon or rectum. "Investigation of MYC and NCAPG2 mutations promises to refine colorectal cancer subtyping, thereby contributing to development of more precise treatment modalities." (PMID 38637125, 2024). "NCAPG2 is linked to the immunosuppressive environment of cancer, suggesting an important role in the etiology of colorectal cancer." (PMID 38637125, 2024). "Aberrations in MYC and NCAPG2 expression or mutations may serve as valuable biomarkers for colorectal cancer, providing insight into early detection, assessing disease severity and predicting prognosis." (PMID 38637125, 2024). "However, the association among MYC, NCAPG2 and colorectal cancer (CRC) is still unclear." (PMID 38637125, 2024). "In particular, MYC, MAD2L1, CENPF, UBE2C, NUF2 and NCAPG2 were identified as highly expressed in colorectal cancer samples." (PMID 38637125, 2024). "MYC and NCAPG2, key players in cancer research, are of paramount importance in unravelling the complexities of colorectal cancer." (PMID 38637125, 2024). "The core genes, namely MYC, MAD2L1, CENPF, UBE2C, NUF2 and NCAPG2, showed elevated expression in colorectal cancer samples, in stark contrast to their comparatively lower expression in normal samples." (PMID 38637125, 2024). "Through a meticulous exploration involving enrichment analysis and pathway analysis, this research aims to shed light on the intricate roles played by MYC and NCAPG2 in the development of colorectal cancer." (PMID 38637125, 2024). "The elevated expression of MYC and NCAPG2 in colorectal cancer is one of the key findings of this study." (PMID 38637125, 2024). "High expression of MYC and NCAPG2 is significantly predictive of clinical outcomes in colorectal cancer patients, indicating their potential clinical relevance." (PMID 38637125, 2024). "Elevated levels of MYC and NCAPG2 in colorectal cancer correlate with poorer prognosis." (PMID 38637125, 2024). "Notably, the core genes (MYC, MAD2L1, CENPF, UBE2C, NUF2, NCAPG2) had differential expression in colorectal cancer samples in comparison to normal samples." (PMID 38637125, 2024). "KIF14, KIF18B, KIF23, KIF4A, KNTC1, NCAPG2, and MCM3 regulate chromosomal integrity, mitotic spindle formation, and DNA replication, processes that are frequently dysregulated in colorectal cancer." (PMID 40405535, 2025). "However, it is not yet clear how MYC and NCAPG2 are involved in colorectal cancer." (PMID 38637125, 2024).
malignant melanoma (2 papers, 2007 to 2024). "NCAPG2 orchestrates the progression of malignant melanoma by fine-tuning both proliferation and metastasis to exert its pro-tumorigenic effects." (PMID 38637125, 2024).
acute myeloid leukemia (1 paper, 2024). Acute myeloid leukemia (AML) is a group of neoplasms arising from precursor cells committed to the myeloid cell-line differentiation. "Besides, it has been shown that STAT3 regulates the transcriptional activity of MYC gene in primitive acute myeloid leukemia cells, invoking the possibility that NCAPG2 might interact with STAT3 and subsequently activate c-MYC expression." (PMID 38166947, 2024).
cervical cancer (1 paper, 2023). A primary or metastatic malignant neoplasm involving the cervix. "Consequently, it is conceivable that dysregulation of NCAPG2 and PLK1 localization and regulation, possibly mediated by HPV-16 E7, may contribute to the pathogenesis and progression of cervical cancer." (PMID 37248471, 2023).
cholangiocarcinoma (1 paper, 2025). A carcinoma that arises from the intrahepatic biliary tree (intrahepatic cholangiocarcinoma) or from the junction, or adjacent to the junction, of the right and left hepatic ducts (hilar cholangiocarcinoma). "However, elevated NCAPG2 expression in cholangiocarcinoma diagnosis does not definitively exclude other malignancies, necessitating careful clinical consideration by surgeons." (PMID 40447854, 2025).
chronic sinusitis (1 paper, 2025). "Besides, hsa-miR-6507-5p was significantly downregulated in chronic sinusitis with nasal polyps, and might serve as a protective factor in the development nasal polyps via targeting NCAPG2 and PRC1." (PMID 41200507, 2025).
Fanconi anemia (1 paper, 2025). Fanconi anemia (FA) is a hereditary DNA repair disorder characterized by progressive pancytopenia with bone marrow failure, variable congenital malformations and predisposition to develop hematological or solid tumors. "The Fanconi anemia pathway and homologous recombination, which is crucial for DNA repair and maintaining genomic stability, was also significantly associated with NCAPG2." (PMID 40447854, 2025).
leiomyosarcoma (1 paper, 2023). An uncommon, aggressive malignant smooth muscle neoplasm, usually occurring in post-menopausal women. "NCAPG2 was upregulated in Pleomorphic Liposarcoma, Leiomyosarcoma, and Myxofibrosarcoma with 2.388 (p = 1.98E-8), 2.540 (p = 1.69E-9) and 2.175 (p = 1.36E-9) fold changes." (PMID 37192046, 2023).
low grade glioma (1 paper, 2022). A grade I or grade II glioma arising from the central nervous system. "However, the prognostic value and immune functions of NCAPG2 in low-grade glioma (LGG) remain unresolved." (PMID 35898895, 2022).
Primary microcephaly (1 paper, 2022). Head circumference below 2 standard deviations below the mean for age and gender at birth. "In addition, also mutations in genes encoding condensin I and II complex members are associated with primary microcephaly, e.g., NCAPD2, NCAPH, NCAPG2 or NCAPD3, which showed altered expression levels in our data as well." (PMID 35099000, 2022).